PTPRM (protein tyrosine phosphatase receptor type M)
Description:
Receptor protein-tyrosine phosphatase that mediates homotypic cell-cell interactions and plays a role in adipogenic differentiation via modulation of p120 catenin/CTNND1 phosphorylation. Promotes CTNND1 dephosphorylation and prevents its cytoplasmic localization where it inhibits SLC2A4 membrane trafficking. In turn, SLC2A4 is directed to the plasma membrane and performs its glucose transporter function.
Synonyms: R-PTP-mu; PTPRL1; RPTPU; hR-PTPu; RPTPM
Tractability: Antibody: UniProt places it where antibodies can reach, with high confidence; its Gene Ontology location is reachable by antibodies, with high confidence; UniProt predicts a signal peptide or a membrane-spanning region; the Human Protein Atlas places it where antibodies can reach. PROTAC: ubiquitination databases record sites on it; its protein half-life has been measured; a small molecule that binds it is known.
Target class: Enzyme; Protein Phosphatase; Receptor tyrosine-protein phosphatase; Tyrosine protein phosphatase; Phosphatase
Gene: Protein-coding gene on chromosome 18 (7,566,782 to 8,406,861, forward strand). Ensembl gene ENSG00000173482.
Subcellular location: Cell membrane
Subcellular location (Human Protein Atlas): Plasma membrane; Primary cilium; Primary cilium tip
Gene Ontology:
Molecular function: cadherin binding; identical protein binding; phosphatase activity; protein binding; protein tyrosine phosphatase activity; transmembrane receptor protein tyrosine phosphatase activity
Biological process: homophilic cell-cell adhesion; negative regulation of angiogenesis; negative regulation of endothelial cell migration; negative regulation of endothelial cell proliferation; neuron projection development; positive regulation of D-glucose transmembrane transport; response to xenobiotic stimulus; retina layer formation; retinal ganglion cell axon guidance; signal transduction; negative regulation of cell migration
Cellular component: adherens junction; cell-cell junction; cytoplasm; lamellipodium; perinuclear region of cytoplasm; plasma membrane; membrane
Genetic constraint (gnomAD): Loss-of-function variants: 38 observed, 149.12 expected, observed/expected ratio (o/e) 0.25, 90% interval 0.2 to 0.33. The upper end of that interval is the gene's LOEUF score, 0.33, which puts it in group 1 of 6, group 1 being the genes least tolerant of losing a copy. Missense variants: 1,322 observed, 1,697.8 expected, observed/expected ratio (o/e) 0.78, 90% interval 0.74 to 0.81. Synonymous variants: 600 observed, 625.09 expected, observed/expected ratio (o/e) 0.96, 90% interval 0.9 to 1.03.
Homologues: Orthologues: chimpanzee PTPRM (99% identical), macaque PTPRM (99% identical), mouse Ptprm (97% identical), rabbit PTPRM (97% identical), dog PTPRM (97% identical), rat Ptprm (97% identical), guinea pig PTPRM (94% identical), pig PTPRM (94% identical), tropical clawed frog ptprm (87% identical), zebrafish si:ch1073-391i24.1 (18% identical). Paralogues in human: PTPRT (65% identical), PTPRK (61% identical), PTPRU (53% identical), PTPRF (30% identical), PTPRD (30% identical), PTPRS (29% identical), PTPRZ1 (23% identical), PTPRG (21% identical), PTPRC (19% identical), PTPRB (19% identical), PTPRA (17% identical), PTPRE (17% identical), and 23 more.
Diseases named in the same sentence as PTPRM in open-access papers:
PTPRM is named in the same sentence as 56 diseases in open-access papers, as found by Europe PMC text mining. Sharing a sentence is not in itself a finding about the gene and the disease. The quoted sentences say what the papers report.
breast carcinoma (9 papers, 2012 to 2023). "Decreased expression of PTPRM in breast cancer was associated with poor prognosis and was negatively correlated with disease-free survival." (PMID 37403117, 2023). "PTPRM expression is downregulated by genetic and epigenetic alterations such as loss of heterozygosity and hypermethylation in breast cancer, colorectal cancer, and acute lymphoblastic leukemia." (PMID 31900385, 2020). "The present study aimed to examine the expression of PTPRM in breast cancer and its association with the disease progression and also the impact of this molecule on breast cancer cell functions." (PMID 23185569, 2012). "PTPRM overexpression is negatively correlated with the progression of colon, neuroendocrine, and breast cancers." (PMID 35626106, 2022). "Sun and colleagues were the first to identify a correlation between decreased PTPRM expression and poor prognosis in breast cancer." (PMID 36139479, 2022). "Of note, their findings revealed that the knockdown of PTPRM resulted in elevated adhesion, invasion and proliferation of breast cancer cells through the regulation of the tyrosine phosphorylation of ERK." (PMID 36139479, 2022). "According to clinical outcome from our follow-up data, PTPRM transcript levels were decreased in patients who died from breast cancer when compared with that of disease free patients (p = 0.012)." (PMID 23185569, 2012). "PTPRM appears to have a similar tumour suppressing role and, for the first time, we demonstrate that in breast cancer there is a significant reduction in transcript levels." (PMID 23185569, 2012). "In the current study, levels of PTPRM transcript in a breast cancer cohort were analysed against the corresponding clinical and pathological data." (PMID 23185569, 2012). "Knockdown of PTPRM increased proliferation, adhesion, invasion and migration of breast cancer cells." (PMID 23185569, 2012). "This indicates that the dephosphorylation of ERK and JNK by PTPRM plays a critical role in coordinating functions of breast cancer cells." (PMID 23185569, 2012). "To examine the involvement of ERK and JNK pathways in the effect of PTPRM knockdown on breast cancer cell motility, we treated the cells with small inhibitors for these pathways." (PMID 23185569, 2012). "Decreased expression of PTPRM in breast cancer is correlated with poor prognosis and inversely correlated with disease free survival." (PMID 23185569, 2012). "Although transcript levels of PTPRM appeared to be reduced in breast cancer tissue in comparison with normal mammary tissues, the difference was not statistically significant." (PMID 23185569, 2012). "The present study investigated the expression of PTPRM in breast cancer and the biological impact of PTPRM on breast cancer cells." (PMID 23185569, 2012). "In summary, results from this study suggest lower expression levels of PTPRM to be a characteristic of breast cancer." (PMID 23185569, 2012). "Our present study has indicated profound roles played by PTPRM in breast cancer cells." (PMID 23185569, 2012). "Knockdown of PTPRM in breast cancer cells was performed using a specific anti-PTPRM transgene." (PMID 23185569, 2012). "Expression of PTPRM protein and gene transcript was examined in a cohort of breast cancer patients." (PMID 23185569, 2012). "The impact of PTPRM knockdown on breast cancer was evaluated using in vitro cell models." (PMID 23185569, 2012). "Moreover, knockdown of PTPRM resulted in elevated adhesion, invasion, and proliferation of breast cancer cells." (PMID 23185569, 2012). "It suggests that the PLCγ1 pathway is not involved in the effect on these breast cancer cells by knockdown of PTPRM." (PMID 23185569, 2012).
glioblastoma (8 papers, 2016 to 2025). The most malignant astrocytic tumor (WHO grade IV). "In contrast, the PTPRM gene, which exhibits low expression in cancers like glioblastoma multiforme and is associated with increased cell migration, was suppressed in SKBR3_HR cells, with a dramatic reduction in promoter H3K4me3 but steady H3K27me3." (PMID 38460162, 2024). "Altered expression, mutations, or aberrant methylation of PTPRM have been described in different malignancies, including glioblastoma." (PMID 32056145, 2020). "A certain level of PTPRM expression was maintained in low-grade astrocytoma samples compared with glioblastoma multiforme." (PMID 37403117, 2023). "Studies addressing the role of PTPRM in human glioblastoma multiforme have also shown that PTPRM expression is frequently downregulated in this malignancy." (PMID 37403117, 2023). "PTEN expression correlated with survival probability in glioblastoma and astrocytoma samples, while for PTPRM such an expression-dependent effect only holds for glioblastoma specimens (data not shown)." (PMID 27586084, 2016). "Moreover, PTPRM is downregulated by miRNA-221/-222 in glioblastoma, suggesting its tumor-suppressor function." (PMID 31900385, 2020). "The phosphorylation of signal transducer and activator of transcription protein 3 (STAT3) is up-regulated in glioblastoma (GBM) cells and is regulated by protein tyrosine phosphatase receptor type M (PTPRM)." (PMID 34225581, 2021). "For DUSP26, PTEN, PTPRM and PTPRT, lower expression levels correlated with poor prognosis, and overexpression of DUSP26 or PTPRT in E98 glioblastoma cells reduced tumorigenicity." (PMID 27586084, 2016). "Notably, seven PTP genes (DUSP26, MTMR4, PTEN, PTPRM, PTPRN2, PTPRT and PTPRZ1) were differentially expressed between grade II-III gliomas and (grade IV) glioblastomas." (PMID 27586084, 2016).
glioma (5 papers, 2012 to 2023). A benign or malignant brain and spinal cord tumor that arises from glial cells (astrocytes, oligodendrocytes, ependymal cells). "The results indicated that PTPRM methylation may be a potential diagnostic and therapeutic biomarker for glioma patients." (PMID 34225581, 2021). "PTPRM has also been proposed as a glial tumor suppressor and is consistently down-regulated in high grade samples in our screen." (PMID 27586084, 2016). "A recent study has shown that PLCγ1 is a target of PTPRM and dephosphorylation of PLCγ1 is a major pathway by which PTPRM suppresses glioma cell migration." (PMID 23185569, 2012). "Reduced PTEN and PTPRM protein levels in glioma specimens have been well documented." (PMID 27586084, 2016). "Recent reports have shown that a reduction in expression of Protein Tyrosine Phosphatase-1B (PTP1B) and T-Cell Protein Tyrosine phosphatase (TC-PTP) reduced ERK phosphorylation in MCF-7 cells, and PTPRM suppressed glioma cell migration by dephosphorylation of PLCγ1." (PMID 23185569, 2012). "The finding that the closely related PTPRT and PTPRM show distinct expression patterns in lower versus high grade gliomas (PTPRU just failed to reach the criteria in the first cohort) and correlate with patient survival, warrants further studies on their role in glioma-associated signaling pathways." (PMID 27586084, 2016).
colorectal cancer (4 papers, 2015 to 2023). A primary or metastatic malignant neoplasm that affects the colon or rectum. "In consistence to the high-density oligonucleotide array data showing CN loss in the region harboring PTPRM locus in colorectal carcinomas, high percentage of LOH was observed." (PMID 25910225, 2015). "The protein tyrosine phosphatase receptor-like gene PTPRM was frequently methylated in sporadic colorectal cancer." (PMID 36966276, 2023). "This pathway analysis may aid to probe the role of PTPRM in the initiation and progression of colorectal cancer pathogenesis." (PMID 25910225, 2015).
lung carcinoma (4 papers, 2020 to 2024). "DDIAS knockdown caused growth inhibition of lung cancer cells through STAT3 inactivation by PTPRM, suggesting DDIAS as a potential therapeutic target in aberrant STAT3-activated lung cancer." (PMID 31900385, 2020). "In this study, we demonstrated that DDIAS promoted IL-6–mediated STAT3 activation in lung cancer cells by competing with PTPRM." (PMID 31900385, 2020). "We newly identified the DDIAS/PTPRM/STAT3 system in lung cancer cells with aberrant STAT3 expression." (PMID 31900385, 2020). "To evaluate the correlation between STAT3 activation and expression of DDIAS and PTPRM, we performed immunohistochemistry (IHC) on 40 human lung cancer tissues." (PMID 31900385, 2020). "DDIAS competes with PTPRM to bind to STAT3, allowing STAT3 Y705 phosphorylation to persist in lung cancer." (PMID 37121974, 2023). "We expect multiple, intertwined crosstalks and interactions between DDIAS/PTPRM and other STAT3 regulation system in lung cancer cells." (PMID 31900385, 2020). "Indeed, DDIAS inhibits PTPRM/STAT3 binding and STAT3 Y705 dephosphorylation, allowing STAT3 activation to persist in lung cancer." (PMID 37121974, 2023). "Thus we show that DDIAS prevents PTPRM/STAT3 binding and blocks STAT3 Y705 dephosphorylation, thereby sustaining STAT3 activation in lung cancer." (PMID 31900385, 2020).
cervical cancer (3 papers, 2020 to 2022). A primary or metastatic malignant neoplasm involving the cervix. "PTPRM is associated with the prognosis of cervical cancer and promotes tumor growth and lymph node metastasis." (PMID 35712349, 2022). "Subsequently, we demonstrated that PTPRM was upregulated in cervical cancer with LNM, correlated with poor prognosis and LNM." (PMID 32826853, 2020). "In this study, we identified PTPRM which was markedly overexpressed in locally advanced cervical cancer from TCGA dataset." (PMID 32826853, 2020). "Furthermore, overexpression of PTPRM promoted cervical cancer cells proliferation, migration, invasion, epithelial-to-mesenchymal transition (EMT), lymphangiogenesis, and LNM in vitro and in vivo." (PMID 32826853, 2020). "Another important finding in our study is PTPRM could promote the expression of VEGF-C in cervical cancer cells, resulting in lymphangiogenesis." (PMID 32826853, 2020). "However, PTPRM is positively correlated with poor prognosis in cervical cancer." (PMID 35626106, 2022). "In order to explore the potential mechanism of PTPRM promoting cervical cancer cell proliferation and metastasis, gene set enrichment analysis (GSEA) was used and the results demonstrated that PI3K/AKT and EMT pathway were correlated to the PTPRM expression." (PMID 32826853, 2020).
colon cancer (3 papers, 2014 to 2023). "In agreement to its tumor suppressive role, loss of function of PTPRM in colon cancer was achieved through LOH and promotor hypermethylation." (PMID 25910225, 2015). "We further showed that, in accordance to Knudson's two-hit hypothesis, inactivation of PTPRM in colon cancer was mainly attributed to loss of heterozygosity and promoter hypermethylation." (PMID 25910225, 2015). "Interestingly, a related protein tyrosine phosphatase, PTPRM, has been identified as an insertional mutagenesis target by L1 retrotransposons in colon tumors." (PMID 24505276, 2014). "We also performed loss-of-function study to knock down the expression of endogenous PTPRM in colon cancer SW620 cells using two independent sh-RNAs that targeted at PTPRM at different regions, and investigated whether loss of PTPRM would contribute to cell transformation." (PMID 25910225, 2015). "First, we measured the expression of PTPRM in colon cancer-derived cell lines cultured in the presence and absence of 5-aza-2′-deoxycytidine (5-aza-dC), a methyltransferase inhibitor." (PMID 25910225, 2015).
small intestinal neuroendocrine tumors (3 papers, 2020 to 2023). "PTPRM overexpression in small intestinal neuroendocrine tumor cell lines reduced cell growth and proliferation and induced apoptosis." (PMID 34306007, 2021). "However, some studies indicated that PTPRM was negatively correlated with the progression of colorectal adenoma-carcinoma, small intestinal neuroendocrine tumors and breast cancer." (PMID 32826853, 2020).
colon adenoma (2 papers, 2015 to 2023). An adenoma that arises from the colon. "We performed quantitative PCR analysis of the genomic and complementary DNA derived from primary mucosa, adenoma, and carcinoma samples, and confirmed the recurrent loss and down-regulation of PTPRM in colon adenomas and carcinomas." (PMID 25910225, 2015). "Since loss of PTPRM locus was a common event in both colon adenomas and carcinomas, functional characterization was further performed." (PMID 25910225, 2015). "Functional analysis further supports that loss of PTPRM contributes to the pathogenic development of colon adenoma-carcinoma sequence." (PMID 25910225, 2015). "By in silico and qPCR analyses, we further demonstrated that the gene and transcript copy numbers corresponding to PTPRM were significantly decreased in both primary colon adenomas and carcinomas in comparison to the non-tumorous tissues." (PMID 25910225, 2015).
colorectal adenoma (2 papers, 2015 to 2020). An adenoma that arises from the colon or rectum. "Our data showed that down-regulation of PTPRM was a frequent event in the colorectal adenomas and carcinomas." (PMID 25910225, 2015).
malaria (2 papers, 2021 to 2022). Malaria is a serious and sometimes fatal disease caused by a parasite that commonly infects a certain type of mosquito which feeds on humans. "The analysis revealed two association signals for mild malaria attacks located within the genes SYT16 (synaptotagmin 16) and PTPRM (protein tyrosine phosphatase receptor type M)." (PMID 35646724, 2022).
adenoma (1 paper, 2015). A neoplasm arising from the epithelium. "We further examined the significance of PTPRM loss using large number of samples by analyzing 26 colorectal datasets, including 5 adenoma and 21 carcinoma datasets, which are available in Oncomine database." (PMID 25910225, 2015). "In consistence to the CN loss of PTPRM locus revealed by in silico approach, PCR analysis revealed that 25% (2 of 8) adenomas and 50% (4 of 8) carcinomas displayed CN loss of PTPRM locus." (PMID 25910225, 2015). "This resulted in the discovery of loss of PTPRM on 18p11.2 in the adenoma and carcinoma samples." (PMID 25910225, 2015). "The Oncomine-based data analysis revealed frequent down-regulation of PTPRM in both adenoma and carcinoma samples." (PMID 25910225, 2015). "Quantitative RT-PCR analyses of an additional set of 9 trios of non-tumor-adenoma-carcinoma samples also showed decreased expression of PTPRM in 56% (5 of 9) adenoma and 67% (6 of 9) carcinomas." (PMID 25910225, 2015).
autoimmune disease (1 paper, 2010). A disorder resulting from loss of function or tissue destruction of an organ or multiple organs, arising from humoral or cellular immune responses of the individual to their own tissue constituents. "PTPRM is a receptor-type protein tyrosine phosphatase, which is of particular interest as a number of protein tyrosine phosphatases have been linked to autoimmune disease, including PTPN22 and PTPN2." (PMID 20659327, 2010).
Autoimmunity (1 paper, 2024). The occurrence of an immune reaction against the organism's own cells or tissues. "We therefore propose that PTPRM hemizygosity conveys susceptibility to Th17-mediated autoimmunity." (PMID 39359478, 2024). "In conclusion, we identified monozygotic triplets concordant for developmental delay and early-onset autoimmunity to harbor an interstitial 18p deletion including PTPRM–a negative regulator of STAT3." (PMID 39359478, 2024). "From this search, we identified PTPRM as a potential candidate gene for autoimmunity/immune dysregulation." (PMID 39359478, 2024). "PTPRM is reported to dephosphorylate and thereby negatively regulate the activation of STAT3, a crucial transcription factor in the immune system with links to autoimmunity." (PMID 39359478, 2024). "Taken together, we propose that the deletion of PTPRM may contribute to the triplets’ autoimmune manifestations by reducing the negative regulation of STAT3 phosphorylation, thereby increasing Th17 cell fractions and promoting autoimmunity." (PMID 39359478, 2024).
borderline epithelial ovarian tumors (1 paper, 2023). "PTPRM had the highest expression rates in normal ovarian and uterine tube tissues, followed by benign and borderline epithelial ovarian tumors; the lowest positive expression rate was observed in EOC tumors." (PMID 37403117, 2023).